USP1 (ubiquitin specific peptidase 1)
Diseases named in the same sentence as USP1 in open-access papers (continued):
Sharing a sentence is not in itself a finding about the gene and the disease.
digestive system cancer (1 paper, 2022). A primary or metastatic malignant neoplasm involving any part of the digestive system. "In this study, three of these four differentially methylated genes have been reported to be associated with digestive system cancers (USP1, CDH4, and IL1RAP)." (PMID 36685967, 2022).
psychiatric disorder (1 paper, 2023). A disorder characterized by behavioral and/or psychological abnormalities, often accompanied by physical symptoms. "Pimozide, an USP1 inhibitor, has been approved by FDA for the treatment of psychiatric disorders, indicating that pimozide is readily available and safe." (PMID 36352191, 2023).
USP1 also shares sentences with these, for which no sentence is quoted: sarcoma (4 papers); triple-negative breast carcinoma (3); cervical cancer (2); esophageal squamous cell carcinoma (2); malaria (2); metabolic disease (2); nasopharyngeal carcinoma (2); Obesity (2); pancreatic cancer (2); renal cell carcinoma (2); bladder tumor (1); cardiovascular diseases (1); cholera (1); cryptorchidism (1); diabetic foot ulcers (1); endometrial cancer (1); Hepatitis B (1); neuroblastoma (1); neuropathy (1); oral squamous cell carcinoma (1); ovarian tumor (1); retinopathy (1); small cell lung carcinoma (1); T-cell acute lymphoblastic leukemia (1); Thyroid Carcinoma (1); uterine corpus endometrial carcinoma (1); uveal melanoma (1); Wolfram syndrome (1).